PTH (parathyroid hormone)
Diseases named in the same sentence as PTH in open-access papers (continued):
Sharing a sentence is not in itself a finding about the gene and the disease.
Hypercalciuria (continued). "Laboratory findings were largely unremarkable aside from episodic hypercalciuria, normal parathyroid hormone levels, and fluctuating vitamin D levels." (PMID 40486414, 2025). "Both groups of patients, with SLC34A1 or SLC34A3 defects, shared a common biochemical pattern, including elevated 1,25(OH)2D and alkaline phosphatase levels, suppressed parathyroid hormone (PTH), and hypercalciuria." (PMID 41008628, 2025). "High levels of PTH in primary hyperparathyroidism (PHPT) significantly increase the risk for calcium kidney stone formation, preceded by hypercalcemia and hypercalciuria." (PMID 39055046, 2024). "First, an ectopic PTH-secreting adenoma was identified, followed by persistently normal PTH levels for over 2 years after surgical resection, despite the presence of hypercalciuria." (PMID 39055046, 2024). "The NC group with GA ≥ 28 weeks had higher vitamin D intake (p < 0.05), hypercalciuria and calcium/creatinine ratio (p < 0.01) and lower parathyroid hormone levels (p < 0.05)." (PMID 39768792, 2024). "In the most severe form, reduced incorporation of minerals in the skeleton results in elevated calcium and phosphate, with reduced PTH levels and hypercalciuria." (PMID 36817604, 2023). "As hypercalciuria, one main risk factor of renal calcifications, often occurs under standard therapy with calcium and vitamin D, treatment with parathyroid hormone is getting more important as it allows to avoid hypercalciuria." (PMID 38027217, 2023). "Patients with ADH1 present with hypocalcemia, hypomagnesemia, hyperphosphatemia, hypercalciuria, and inappropriately low or normal levels of PTH." (PMID 36812896, 2023). "First, we did not fully investigate values related to calcium metabolism, such as ionized calcium, intact parathyroid hormone, 1,25-dihydroxyvitamin D3, or the presence of hypercalciuria." (PMID 37964965, 2023). "Unlike XLH patients, HHRH patients have high 1,25OHD levels, which result in hypercalciuria due to increased intestinal Ca absorption and decreased PTH-induced Ca absorption in the distal renal tubules." (PMID 37638278, 2023). "Serum biochemistry showed high calcium and PTH levels along with hypercalciuria and high creatinine." (PMID 35038313, 2022). "Dosages need to be adjusted in order to keep PTH levels in the normal range and to avoid hypercalciuria." (PMID 35352187, 2022). "In parallel with the observed hypercalciuria, parathyroid hormone (PTH) progressively and significantly declined during bedrest reaching a significantly lower value already at day 3 compared to pre-bedrest and did not recover in the two post bedrest days." (PMID 35514354, 2022). "High serum PTH concentrations would promote greater stimulation of 1.25(OH)2D synthesis through renal hydroxylation of 25(OH)D, which, in turn, may increase filtered calcium load and predispose to hypercalciuria and renal calcifications, even with serum calcium in the normal range." (PMID 35437440, 2022). "The European Society of Endocrinology Expert Consensus recommends a trial of hydrochlorothiazide to determine if improving the hypercalciuria can resolve the elevation in PTH concentrations." (PMID 36382756, 2022). "We observed typical HVD biochemical features in SLC34A3 relatives’ group, namely hypercalciuria in 8/11 cases, low serum PTH in 6/11 cases, high 1,25-(OH)2D in 9/11 cases." (PMID 34721296, 2021). "Generally, impaired function of Na-P cotransporter results in P wasting and hypophosphatemic rickets, short stature, bowing, normal or reduced FGF23 levels, hypercalciuria, elevated 1,25(OH)2D3 and low PTH levels." (PMID 34068220, 2021). "As discussed in previous paragraphs, microgravity-induced bone loss and demineralization raises the risk for kidney stone formation, as elevated blood Ca2+ levels suppress PTH secretion manifesting with hypercalciuria." (PMID 33925533, 2021).
Hypercalciuria (continued). "Those individuals with fasting hypercalciuria along with an increased or high/normal parathormone (PTH) are defined as having “renal leak” as the primary mechanism, with the basic abnormality resting within the nephron." (PMID 34977081, 2021). "Hereditary hypophospatemic rickets with hypercalciuria (HHRH) is a group of disorders featuring increased renal sensitivity to PTH." (PMID 33815294, 2021). "All patients presented with suppressed PTH except one who had PTH levels at low normal values in parallel to normal blood calcium levels, but suppressed PTH levels in follow up, hypercalciuria and nephrolithiasis, and was included into this cohort (patient 3)." (PMID 34858904, 2021). "Low concentrations of PTH, which normally induce reabsorption of Ca2+ from the primary filtrate, result in relative hypercalciuria, which is characterized by urinary Ca:Cr ratios that are within or above the reference range." (PMID 34068220, 2021). "Clinical and biochemical features of the clusters of postmenopausal women with reduced bone mineral density and persistent hypercalciuria identified on the base of serum calcium, phosphate and PTH." (PMID 34977081, 2021). "One patient was referred at the age of 5 for hypercalciuria and nephrocalcinosis, normal serum calcium and low PTH." (PMID 34721296, 2021). "Bilateral nephrocalcinosis, mild hypomagnesemia, hypercalciuria, elevated fractional excretion of magnesium, increased parathyroid hormone, and decreased glomerular filtration rate were found." (PMID 32869508, 2020). "For infants on phosphorous, calcium, vitamin D, or calcitriol treatments, the goals are to normalize PTH levels, monitor for hypercalciuria, and to normalize phosphorus levels by limiting urinary phosphorus wasting, as evidenced by increases in TRP." (PMID 33348603, 2020). "It has been reported that the depletion of phosphate is related to hypercalciuria with a resistance to PTH actions to stimulate tubular reabsorption of Ca, to inhibit tubular reabsorption of phosphate, and consequently raises serum Ca in blood." (PMID 30609750, 2019). "The aims of the treatment were to achieve normocalcemia, to maintain PTH levels within normal limits and to avoid hypercalciuria." (PMID 30282619, 2019). "Laboratory assessments include serum calcium, phosphate, ALP and PTH levels, as well as urinary calcium and creatinine for hypercalciuria." (PMID 29280738, 2017). "The main goal is to suppress PTH, maintain serum calcium in the normal range and prevent hypercalciuria." (PMID 29280738, 2017). "The decrease in serum phosphate promotes biosynthesis of 1,25(OH)2D, which leads to increase in the absorption of intestinal calcium, suppressed PTH and development of hypercalciuria and nephrocalcinosis." (PMID 29280738, 2017). "Hypercalciuria is a particularly difficult problem in ADH1 due to two independent mechanisms: low PTH and activation of the CASR in the renal TAL." (PMID 27803672, 2016). "At the ninth month of the follow-up, as calcitriol treatment was used in a dose higher than that prescribed (3x0.5 μg/dose instead of 3x0.25 μg/dose), serum PTH level decreased below normal ranges and urinary analysis revealed hypercalciuria." (PMID 27353739, 2016). "Low serum PTH levels, normal serum 25-hydroxy vitamin D and 1,25-dihydroxy vitamin D, and hypercalciuria are the other typical biochemical findings of the disease." (PMID 27086862, 2016). "A similar dissociation between increased calcium excretion and PTH levels has been reported in idiopathic hypercalciuria patients with high propensity to form kidney stones." (PMID 27442254, 2016). "FGFR1 effects to diminish membrane expression of TRPV5 in Fgfr1DT-cKO mice likely accounts for both the inability of PTH and intracellular calcium transport pathways to compensate for the hypercalciuria." (PMID 26839958, 2016). "First, low concentrations of PTH, which normally induce reabsorption of calcium from the primary filtrate, result in relative hypercalciuria." (PMID 27803672, 2016).
Hypercalciuria (continued). "In murine models, aldosterone infusion increased PTH levels through natriuresis and subsequent hypercalciuria that also decreased ionized calcium and released PTH." (PMID 26161274, 2015). "In patients with HHRH, 1,25-diOH-vitamin D synthesis is enhanced and PTH secretion often suppressed, both conditions favoring hypercalciuria; therefore, patients require treatment with phosphate supplements solely." (PMID 24550322, 2014). "Activating calcium sensing receptor (CaSR) mutations cause autosomal dominant hypocalcemia (ADH) characterized by low serum calcium, inappropriately low PTH and relative hypercalciuria." (PMID 25506941, 2014). "Several studies have shown abnormally low levels of 1,25(OH)2D3, hypercalciuria, low parathyroid hormone, and low to normal levels of calcium, magnesium and phosphate." (PMID 24986711, 2014). "Trpv5682P/682P mice also had normal plasma parathyroid hormone but increased 1,25-dihydroxyvitamin D3 concentrations without increased bone resorption, consistent with a renal defect for the hypercalciuria." (PMID 23383183, 2013). "The goal of therapy is to maintain serum total and ionized calcium level within reference range while avoiding hypercalciuria and to suppress PTH level to normal." (PMID 22779017, 2012). "The primary defect in tubular phosphate absorption in NPT2a −/− mice stimulates calcitriol synthesis by the kidney, which in turn increases intestinal absorption of calcium and phosphate and inhibits PTH secretion, resulting in hypercalciuria." (PMID 17464515, 2007). "Furthermore, serum albumin-adjusted calcium levels that are persistently outside the normal range and hypercalciuria are additional indications for PTH replacement therapy." (PMID 40794165, 2025). "Therefore, the goal of treatment is to maintain serum PTH within the upper normal range, promoting calcium reabsorption in the kidneys and preventing hypercalciuria and the formation of renal stones, while minimizing adverse effects on bone mineralization." (PMID 41170251, 2025). "The PTH remained low/low-normal and the hypercalciuria persisted." (PMID 40765620, 2025). "Interestingly, PTH sensitivity in the distal tubules is preserved, which protects against hypercalciuria and nephrolithiasis, features that are seen in classical hypoparathyroidism." (PMID 41170251, 2025). "The most important biochemical values are serum phosphate (to assess efficacy of burosumab treatment), ALP (as a measurement of rickets/osteomalacia activity), PTH (to detect hyperparathyroidism), and calcium-to-creatinine ratio in urine (to detect hypercalciuria)." (PMID 40295317, 2025). "Additionally, among infants with a GA ≥ 28 weeks’, data showed homogeneity along with clear evidence of hypercalciuria, higher daily vitamin D intake and lower PTH level in the first month of life." (PMID 39768792, 2024). "High 1,25 (OH)2D serum values can stimulate intestinal calcium absorption independent of PTH (low values) and cause absorptive hypercalciuria." (PMID 38133239, 2023). "However, these treatments to correct serum calcium levels suppress serum PTH levels, and can lead to the development hypercalciuria and renal calcification." (PMID 35497370, 2022). "However, osteopenia/low bone mineral density, hypercalciuria, high-normal to elevated 1,25(OH)2D and low PTH point to the diagnosis of HHRH/NPHLOP." (PMID 33815294, 2021). "Conceptually, TZD increases tubular calcium reabsorption, thus providing protection against hypercalciuria, and with that may raise serum calcium, suppress PTH secretion, and improve bone metabolism." (PMID 34977081, 2021). "Therefore, studies with teriparatide, as an additional countermeasure for circulating PTH fall in microgravity and hypercalciuria, would be interesting in future space missions." (PMID 33925533, 2021). "Whether the reduced PTH levels observed in our population contribute to hypercalciuria and renal compromise needs further exploration." (PMID 32219087, 2020).
Hypercalciuria (continued). "There are also examples of primary bone defects that are associated with hypercalciuria without increased PTH." (PMID 19874200, 2010). "This action of the parathyroid hormone in combination with the effect of idRTA may have led to the much lower serum calcium, hypercalciuria and subsequently more severe clinical features in the subjects with idRTA." (PMID 20699008, 2010). "In contrast, conventional therapy does not restore the calcium-retaining effect of PTH in the kidney and is associated with iatrogenic complications resulting from hypercalciuria and consequent long-term complications including nephrocalcinosis, nephrolithiasis, and renal dysfunction." (PMID 39376010, 2025). "PTH treatment may be a therapeutic option for infants, replacing the physiological role of the missing hormone in maintaining normal calcium levels and limiting complications related to uncontrolled hypercalciuria." (PMID 39246904, 2024). "Absorptive hypercalciuria can possibly explain the calcite formation on farm A. In the case of absorptive hypercalciuria, there is high intestinal Ca absorption, resulting in enhanced filtered load and reduced tubular reabsorption in the kidney because PTH values are low." (PMID 38133239, 2023). "It has previously been hypothesized that hypercalciuria, a characteristic feature of patients with Bartter syndrome type I and type II, may contribute to increased PTH secretion, as a physiological response to maintain serum calcium within the normal range despite excessive renal calcium loss." (PMID 35137195, 2022). "Moreover, a recent review by Mannstadt et al16 shows that conventional treatment increases the risk of hypercalciuria due to increased excretion of calcium in the urine caused by the lack of PTH‐induced reabsorption of calcium in the kidneys." (PMID 34277992, 2021). "Alternatively, hypercalciuria may have contributed to persistently elevated PTH levels." (PMID 33210066, 2020). "Careful monitoring of plasma calcium, PTH, creatinine, and 24-h urinary calcium excretion is required in order to prevent tertiary hyperparathyroidism, induced by phosphate overdose, and hypercalciuria with nephrocalcinosis and renal insufficiency, resulting from calcitriol overtreatment." (PMID 24550322, 2014). "PTH most likely has no causal role in the development of hypercalciuria in acromegaly." (PMID 24616756, 2013). "The occurrence of hypercalciuria in patients with PHPT is somewhat paradoxical, since the primary renal effect of PTH is to increase renal tubular reabsorption Ca (TRCa)." (PMID 41377934, 2025). "Among 1671 patients with hypercalciuria, 91 patients had a final diagnosis of PHPT (postload ionized calcium [iCa] > 1.31 mmol/L and parathyroid hormone [PTH] > 30 pg/mL)." (PMID 38497124, 2024). "PTH stimulates the hydroxylation of 25-OHD, leading to elevated calcitriol levels, which contribute to hypercalciuria and multiple calculus formation." (PMID 39020280, 2024). "Thus, for hypercalciuria to occur in PHPT, the PTH-dependent increased TRCa must be overcome by the increased filtered load, which usually does not occur until serum Ca level exceeds 12 mg/dl." (PMID 41377934, 2025). "According to available data, the relationships between vitamin D supplementation, serum 25(OH)D concentration, parathyroid hormone level, hypercalciuria and development of NC in preterm infants are not well established." (PMID 39768792, 2024). "Unlike PTH, which acutely lowers urine calcium clearance, we noted hypercalciuria in renal-specific SIK mutant mice." (PMID 36862513, 2023). "The nonsteroidal anti-inflammatory drugs thus enhanced growth velocity, alleviated hypercalciuria, and increased PTH-stimulated urinary phosphorus excretion without significantly affecting renal function." (PMID 37908481, 2023). "In the absence of PTH, the renal tubular resorption of calcium is adversely affected, leading to hypercalciuria." (PMID 33133833, 2020).
Hypercalciuria (continued). "In case II, ALP and PTH significantly improved without the development of hypercalciuria; a small and not significant reduction in PTH and ALP level was seen in case V despite increasing doses of both drugs." (PMID 32299476, 2020). "Hypercalciuria is also found in these patients, and specifically hypercalciuria in the absence of elevated parathyroid hormone or serum calcium." (PMID 31312622, 2019). "During follow-up, it is important to monitor the occurrence of hypercalciuria (urinary calcium greater than 4 mg/kg/day), due to the absence of PTH during treatment with calcium and vitamin D (A)." (PMID 29694629, 2018). "Unlike patients with primary hypoparathyroidism, PHP cases do not develop hypercalciuria, which shows that the anti-calciuric effect of PTH in the thick ascending limb remains intact." (PMID 27425121, 2017). "Although theoretically, it could be a direct result of excessive PTH as in cases of PHPT, the presence of nonfasting hypercalciuria in our case could also be a coincidental finding, like other cases of enteric hypercalciuria without PTH derangements." (PMID 39055046, 2024). "However, the cross-sectional design of the study and significant heterogeneity of patient treatments, do not allow excluding a possible role of hypercalciuria in promoting PTH secretion." (PMID 35137195, 2022). "Normal calcium and PTH levels without hypercalciuria were tried to be achieved." (PMID 27353739, 2016). "Thus the dosage of calcitriol and elemental Ca should be individualized to maintain normalized PTH and serum calcium levels without hypercalciuria." (PMID 24651309, 2014). "Moreover, phase 2 clinical studies have demonstrated that intravenous administration of NPSP795 increased PTH concentrations in five ADH1 patients, and oral administration of encaleret increased plasma calcium and PTH without causing hypercalciuria in 13 ADH1 patients." (PMID 40086735, 2025). "Taken together, all these factors related to hypercalciuria may make it difficult to distinguish PHPT, which may benefit from parathyroidectomy, from non-autonomous PTH-related conditions, where surgery should be avoided as highly probable ineffective in resolving hypercalciuria." (PMID 34977081, 2021). "Furthermore, other factors that can elevate PTH in apparently healthy subjects, both recognized as a cause of SHPT and included in the differential diagnosis of normocalcemic PHPT such as hypercalciuria and conditions of malabsorption, were not excluded in the previous studies." (PMID 30916167, 2019). "PTH levels in most studies in children with IH have been found to be normal and not related to BMD, while at the same time, there was a negative correlation between hypercalciuria and BMD." (PMID 40416164, 2025).